PPP1R2C (PPP1R2 family member C)
Description:
Functions as a protein phosphatase inhibitor. It inhibits activity of the catalytic subunit of PP1 and weakly inhibits the activity of myosin-associated phosphates.
Synonyms: I-4; PPP1R2P9
Tractability: No criterion of Open Targets' tractability assessment is met for any kind of drug.
Gene: Protein-coding gene on chromosome X (42,777,366 to 42,778,163, reverse strand). Ensembl gene ENSG00000102055.
Gene Ontology:
Molecular function: protein binding; protein phosphatase inhibitor activity
Biological process: intracellular signal transduction; regulation of signal transduction
Homologues: Orthologues: chimpanzee PPP1R2C (98% identical), macaque PPP1R2C (91% identical), dog PPP1R2C (50% identical), Drosophila melanogaster I-2 (26% identical), Drosophila melanogaster CG6380 (25% identical), Caenorhabditis elegans szy-2 (24% identical), Drosophila melanogaster CG12620 (15% identical). Paralogues in human: PPP1R2 (43% identical), PPP1R2B (42% identical).
Diseases named in the same sentence as PPP1R2C in open-access papers:
PPP1R2C is named in the same sentence as 7 diseases in open-access papers, as found by Europe PMC text mining. Sharing a sentence is not in itself a finding about the gene and the disease. The quoted sentences say what the papers report.
Graves disease (1 paper, 2025). Graves' disease is an autoimmune disorder that leads to overactivity of the thyroid gland (hyperthyroidism).It is caused by an abnormal immune system response that causes the thyroid gland to produce too much thyroid hormones. "XIST, PPP1R2C, CALHM6, AL672277.1, TSIX, SHROOM1, ADTRP, JUND, SGK1, CHKA, AO008569.1, MAP7D2, and AIF1 were down-expressed genes in TS compared with both the healthy female and the female patient with Graves’ disease." (PMID 39851522, 2025).
PPP1R2C also shares sentences with these, for which no sentence is quoted: breast carcinoma (1 paper); cancer (1); infection (1); skin cancer (1); Turner syndrome (1); uterus tumors (1).